TSPO (translocator protein)
Diseases named in the same sentence as TSPO in open-access papers (continued):
Sharing a sentence is not in itself a finding about the gene and the disease.
Cognitive impairment (36 papers, 2012 to 2025). Abnormal cognition is characterized by deficits in thinking, reasoning, or remembering. "Recently, the results of meta-analyses of TSPO levels in mild cognitive impairment and AD further supported the association of increased neuroinflammation during the progression of mild cognitive impairment and AD, relative to healthy controls." (PMID 35903248, 2022). "Association between cognitive impairment and reduced TSPO expression has been reported in Alzheimer’s disease, early-stage schizophrenia, alcohol dependence, and Hepatitis C–associated encephalopathy." (PMID 33978829, 2021). "Conversely, lentiviral-mediated TSPO overexpression decreases the cognitive deficits associated with LPS." (PMID 32839410, 2020). "In support of this, cumulative RHI exposure has recently been associated with cognitive impairment later in life and TSPO PET ligands for activated microglia have shown elevated activity in retired NFL players at risk for CTE." (PMID 27793189, 2016). "In addition, our data, showing a reduction of pathological markers when TSPO levels are lowered, are consistent with observations in humans, where higher TSPO levels are associated with greater cognitive impairment." (PMID 41152868, 2025). "The TSPO-PET imaging would directly test the hypothesized neuro-immune reflex arc believed to be responsible for the immunodeficiency associated with cognitive impairment." (PMID 37901041, 2023). "In addition, high levels of TSPO are mostly associated with elevated cognitive deficits." (PMID 41152868, 2025). "These interesting data gave reason to hypothesize that downregulation of TSPO in the brain could be a risk factor for the etiology of neuroinflammatory cognitive impairment, and increased TSPO might be a novel pharmacological treatment strategy for cognitive impairment." (PMID 27803668, 2016). "To evaluate if TSPO knockout directly affects Tau-related neuropathology and cognitive deficits, independently of Aβ pathology, we performed additional experiments." (PMID 41152868, 2025). "The results demonstrated that TSPO overexpression significantly ameliorated cognitive deficits in the model mice by promoting the biosynthesis of progesterone and isoprogesterone, an effect not observed in the finasteride intervention group." (PMID 40584531, 2025). "Finaly, in TSPO−/− mice we demonstrated that Tau-induced cognitive deficits were inhibited as compared to WT, demonstrating the beneficial effect of TSPO reduction." (PMID 41152868, 2025). "Whilst relatively few TSPO-PET studies have focused on cognitive impairment in PD, there is an expanding body of PET data acquired using both 11C-PK11195 and second generation TSPO ligands in PD compared with controls." (PMID 37757857, 2024). "Early and often small studies described null or even positive associations between TSPO PET signal and cognition—in particular, in patients with mild cognitive impairment." (PMID 36883644, 2023). "In a previous study, modulation of neuroinflammation during sepsis by blocking TSPO using an antagonist decreased brain cytokine expression and prevented cognitive impairment." (PMID 35606817, 2022). "The coadjuvant treatment of the TSPO antagonist, PK-11195, improved mitochondrial function and reduced microglial activation and cognitive impairment." (PMID 35606817, 2022). "Supporting the idea of early implication of TSPO in pathology, it has been shown that patients with high initial rates of TSPO have lower cognitive deficits in the following years." (PMID 32839410, 2020). "The purpose of our present study was to investigate the effects of lentiviral-mediated hippocampal overexpression of the TSPO in a mouse model of LPS-induced cognitive impairment." (PMID 27803668, 2016). "In an effort to better understand the anti-cognitive-impairment effect of hippocampal overexpression of TSPO, we then tested the possible mechanisms." (PMID 27803668, 2016).
Cognitive impairment (continued). "To this end, we performed TSPO-PET imaging in 16 patients with subjective cognitive decline (SCD)/ mild cognitive impairment (MCI), 16 AD patients and 14 unaffected controls, staged by Aβ and tau cerebrospinal fluid (CSF) levels, and investigated their TSPO signal in the respective OBs." (PMID 40781079, 2025). "Indeed, the exogenous overproduction of Tau induced higher densities of phospho-Tau and a higher cognitive impairment in the presence of TSPO." (PMID 41152868, 2025). "Since the Tau pathology correlates to the cognitive deficits observed in AD patients, our observation of decreased Tau and Tau-induced cognitive deficits suggests a strong translational potential of inhibiting TSPO." (PMID 41152868, 2025). "The contradictory results across different studies using TSPO variables may be explained by methodological differences in the studies and how cognitive impairment was assessed." (PMID 30930767, 2019). "Moreover, TSPO overexpression in the CA1 region of the hippocampus improved LPS-induced cognitive impairments in mice." (PMID 31822279, 2019). "We first investigated whether overexpression of TSPO could reverse the cognitive impairment induced by LPS." (PMID 27803668, 2016). "Our data suggested that the LPS-induced cognitive impairment could be reversed by TSPO overexpression in the dentate gyrus." (PMID 27803668, 2016). "However, the exact role that TSPO plays in neuroinflammation-induced cognitive impairment is still elusive." (PMID 27803668, 2016). "As the lentiviral vector stimulated hippocampal TSPO signaling efficiently, we then examined whether this molecular change modified cognitive performance in an LPS-induced cognitive impairment model." (PMID 27803668, 2016). "However, within Braak II (β = − 0.03 ± 0.02; P = 0.08), Braak III (β = − 0.02 ± 0.01; P = 0.08), Braak IV (β = − 0.02 ± 0.01; P = 0.06) there were trends to suggest that influenza vaccine lowered the TSPO signal in TREM2 p.R47H carriers compared to mild cognitive impairment participants." (PMID 37990275, 2023). "Thus, in summary, it may be postulated that TSPO-dependent negative regulatory effects may play a role in the cognitive impairment affecting meningitis survivors." (PMID 31901235, 2020). "Furthermore, TSPO overexpression rescues LPS-induced cognitive impairment." (PMID 31536603, 2019). "Therefore, we hypothesized that Lv-TSPO and the subsequent synthesis of allopregnanolone targeting adult neurogenesis may be beneficial for the improvement of cognitive impairment." (PMID 27803668, 2016). "Our results suggest that local overexpression of TSPO in the hippocampal dentate gyrus alleviated LPS-induced cognitive deficits, and its effects might be mediated by the attenuation of inflammatory cytokines, inhibition of microglial activation, and promotion of neurogenesis." (PMID 27803668, 2016). "It should be noted that for the key comparison of TSPO signal between the TREM2 p.R47H carrier group and mild cognitive impairment group, the effect of the 8 years age difference, while needing to be acknowledged, is likely to be marginal." (PMID 37990275, 2023). "For the subgroup of participants undergoing repeat TSPO-PET scans, the mild cognitive impairment group was older than the TREM2 p.R47H group (70.7 vs 61.7; P = 0.03)." (PMID 37990275, 2023). "In a recent TSPO PET study, neuro-psychiatric and cognitive impairments in treated HIV-positive patients were shown to be correlated closely to cerebral inflammation." (PMID 37259424, 2023). "Compared to participants with mild cognitive impairment, TREM2 carriers had lower TSPO signal in Braak II (P = 0.04) and Braak III (P = 0.046) regions, despite having a similar burden of tau and amyloid." (PMID 37990275, 2023). "TSPO-PET could potentially be used as an imaging biomarker for microglial activation and long-term cognitive impairment post-meningitis." (PMID 31901235, 2020).
Cognitive impairment (continued). "Surprisingly, however, cognitive deficits in DFP-intoxicated rats did not vary according to TSPO phenotype or seizure severity score." (PMID 27733171, 2016). "Also, neuroimaging studies using positron emission tomography (PET) tracers for microglial activation, such as translocator protein (TSPO) ligands, demonstrated spatial overlap with cognitive deficits coupled with stronger PI3K pathway activation of the given region." (PMID 40806341, 2025). "Importantly, TSPO−/− mice injected with the Tau vector displayed the same level of total Tau but a reduction in phospho-Tau and no cognitive impairments, as compared to WT injected mice." (PMID 41152868, 2025). "In addition, the data presented here demonstrate a beneficial effect of the absence of TSPO in the early stages of the disease and on Tau-induced cognitive deficits." (PMID 41152868, 2025). "Reduced TSPO signal was found in Braak II (η2 = 0.31; F = 5.41; P = 0.04) and III (η2 = 0.29; F = 4.95; P = 0.046) regions of interest between TREM2 p.R47H carriers and mild cognitive impairment participants, which remained significant after PVC application (Braak II: P = 0.03; Braak III: P = 0.03)." (PMID 37990275, 2023).
Anxiety (35 papers, 2013 to 2026). Intense feelings of nervousness, tension, or panic often arise in response to interpersonal stresses. "Moreover, greater TSPO levels in these brain areas were associated with stress and anxiety and higher circulating C-reactive protein (CRP) levels in cannabis users." (PMID 35558424, 2022). "In addition, a human single nucleotide polymorphism of TSPO (A147T) is associated with different psychiatric disorders, like bipolar disorder, anxiety, and panic attacks, along with cancer." (PMID 33652554, 2021). "Interestingly however, the TSPO expression along the lesion edges at day 21 correlated with the long-term outcome in pentylenetetrazol-evoked seizure susceptibility and anxiety in open field test." (PMID 31474824, 2019). "However, little is known regarding the roles and the underlying mechanisms of TSPO in chronic pain-induced anxiety-like behaviors." (PMID 25889665, 2015). "However, little is known about the functions and the underlying mechanisms of TSPO in chronic pain-induced anxiety-like behaviors." (PMID 25889665, 2015). "However, changes in TSPO levels have been previously linked to changes in brain steroid levels and associated with neuropathology, including neurodegenerative disorders, brain injury, anxiety, and mood disorders." (PMID 26925573, 2016). "Koumine treatment significantly reduced anxiety-like behaviors and lowered plasma ACTH and corticosterone levels; its anxiolytic effects were linked to TSPO interaction." (PMID 40508224, 2025). "We observed a reduction of anxiety (exploration time of open arms, duration of head-dipping) in TSPO−/− animals 1 month after the injection of Tau." (PMID 41152868, 2025). "Neurosteroids have similarly been closely tied to the anxiolytic effects of TSPO, with ligands etifoxine being approved for treating anxiety and brexanolone, the aqueous formulation of allopregnanolone, for treatment of postpartum depression." (PMID 37416505, 2023). "Fifth, four cancer survivors were taking sedatives (likely to treat anxiety and/or poor sleep health), where preliminary evidence has suggested the potential for sedatives to block TSPO uptake." (PMID 37751068, 2023). "Another possibility is that the presence of TSPO in neurons is related to its anxiolytic effect, specifically in the management of anxiety and neuroplasticity." (PMID 37416505, 2023). "TSPO was initially designated as a peripheral-type benzodiazepine receptor, which is the binding site for benzodiazepines used to treat patients with anxiety, convulsions, or insomnia." (PMID 36071748, 2022). "Etifoxine, a benzoxazine-based anti-anxiety compound, is an exogenous ligand of the 18-kDa translocator protein (TSPO) with high affinity." (PMID 36212660, 2022). "This correlation between elevated TSPO and psychological alterations like chronic stress and anxiety in cannabis users aligned with several preclinical reports." (PMID 35558424, 2022). "These unique effects make TSPO an alluring target for the development of novel pharmaceuticals for psychiatric disorders such as anxiety, as well as sleep disorders." (PMID 35444539, 2022). "Studies showed that Wuling capsule played a role in anti-anxiety through increasing TSPO-mediated mitophagy." (PMID 31894843, 2020). "Taken together, the results presented here support the role of TSPO in hormone-stimulated steroid biosynthesis and the role of TSPO ligands in diseases with steroid-dependent stress and anxiety components." (PMID 29074640, 2017). "Here, we report that the activation of TSPO by ZBD-2 attenuates chronic pain-induced anxiety-like behaviors by regulating the balance between GABAergic and glutamatergic transmission in the BLA of hindpaw CFA-injected mice." (PMID 25889665, 2015). "Together, these data suggest that TSPO plays a role in neurosteroid production, hence affecting anxiety states, making it a potential target for anxiolytic drugs." (PMID 25345894, 2014).
Anxiety (continued). "In addition, paeoniflorin has shown positive effects on Translocator Protein (TSPO), an 18 kDa protein with known anti-anxiety and anti-depressant properties." (PMID 41409594, 2025). "Our results on etifoxine for startle potentiation to P-threat together with (pre-) clinical findings of effects on particular components of anxiety call for further studies that investigate not only a possible specific indication of the ligand but also the use of TSPO as a biological disease marker." (PMID 35278124, 2022). "TSPO may be pivotalin the comorbidity of AD and anxiety through the synthesis of neurosteroids by promoting thecholesterol transport to the inner mitochondrial membrane, which is the rate-limiting stepin neurosteroidogenesis." (PMID 34819201, 2021). "However, the decrease in anxiety levels observed in Ad-Tau TSPO−/− mice may represent a side effect and warrants further investigation to be fully understood." (PMID 41152868, 2025). "The authors speculated that these findings might be due to factors such as hormone-mediated phasic changes in TSPO expression, tonic changes due to stress/anxiety related to the procedure, or alterations in blood cholesterol levels due to food intake between the scans." (PMID 33796956, 2021). "There is growing interest in the role of TSPO in the pathophysiology of anxiety/affective disorders, based on alterations in neurosteroid concentrations in these diseases and experimental data showing TSPO targeting drugs might be efficacious in anxiety disorders." (PMID 23942012, 2013). "Thus, compounds such as etifoxine and GD-23 that target TSPO show potential as novel non-benzodiazepine treatments for anxiety, given their role in neurosteroid synthesis and the modulation of neuroinflammation." (PMID 40508224, 2025).
breast carcinoma (32 papers, 2014 to 2025). "Finally, a higher global deficit score (GDS) was weakly associated with inflammation on TSPO-PET in the frontal lobe after CTx in breast cancer." (PMID 34919195, 2022). "In breast cancer, TSPO expression, nuclear localization, and TSPO-mediated cholesterol transport into the nucleus have been associated with cancer cell proliferation and expression of an aggressive phenotype, with a correlation between TSPO expression and advanced stages of this malignancy." (PMID 31661894, 2019). "IR700DX-6T induced apoptosis of TSPO-positive breast cancer cells in vitro and exponentially inhibited in vivo tumor growth in MDA-MB-231-bearing mice." (PMID 40243613, 2025). "Further, TSPO was found up-regulated in colorectal and breast cancer, where it promotes the malignancy of aberrant cells." (PMID 40352930, 2025). "Increased TSPO level was observed in several types of neoplastic tissue, including breast cancer, colon cancer, brain cancer, prostate cancer, esophageal cancer, endometrial carcinomas, ovarian cancer, and several other types of cancer cells." (PMID 38675106, 2024). "Translocator protein (TSPO) ligand is highly expressed in most of the cancer including breast cancer." (PMID 38961887, 2024). "Western Blot confirmed the expression of TSPO in the 4T1 cells, compared to other human breast cancer cell lines." (PMID 36559209, 2022). "The significant reduction in TSPO radioligand uptake in the 4T1 mammary cancer model after macrophage depletion suggests that the inflammatory uptake is predominant in this tumor." (PMID 36559209, 2022). "It should be noted that increased content of TSPO has been observed in a wide variety of cancer, including brain cancers, breast cancers, prostate cancers, colon cancers and hepatic carcinomas and, therefore, it is a biomarker in therapeutic diagnosis." (PMID 34638588, 2021). "Can neuroinflammation changes be detected in chemotherapy-treated patients with breast cancer using translocator protein [18F]DPA714 simultaneous positron emission tomographic- and magnetic resonance imaging?" (PMID 34439351, 2021). "Wu and Gallo (2013) demonstrated, by means of transient overexpression or silencing of TSPO, that TSPO contributes to the migration of breast cancer cells." (PMID 33066460, 2020). "In 1999, we reported that the high TSPO expression levels in aggressive breast cancer cells correlated with perinuclear/nuclear localization of TSPO, TSPO-mediated cholesterol transfer into nucleus and increased cell proliferation." (PMID 33383772, 2020). "In particular, TSPO overexpression in a poorly migratory breast cancer cell line resulted in increased migration, whereas the silencing of TSPO in a highly invasive breast cancer cell line decreased migratory capabilities." (PMID 33066460, 2020). "A previous study showed that TSPO expression is regulated by the binding of Sp1, Sp3 and/or Sp4 to the proximal promoter region in human breast cancer cell lines, and a similar sequence was observed in the mouse Tspo gene." (PMID 31536603, 2019). "The heterogeneity of cell types expressing TSPO in metastatic deposits was also proved by Zheng and colleagues after subcutaneous inoculation of the high TSPO MDA-MB-231 breast cancer line and low TSPO MCF-7." (PMID 27077069, 2016). "TSPO nuclear localization has been reported before, particularly in breast cancer cells, where it is involved in cell proliferation." (PMID 27608010, 2016). "The mouse mammary carcinoma 4T1 known to express negligible TSPO was injected into the brain or heart of the animals to explore the early changes occurring in astrocytes and microglia." (PMID 27077069, 2016). "Previous studies have reported dysregulated TSPO expression across various malignancies, including breast cancer, head and neck squamous cell carcinoma, and oral squamous cell carcinoma, where its expression levels correlate with tumor aggressiveness and patient prognosis." (PMID 40936684, 2025).